ENSG00000267699 (novel protein)
Gene: Protein-coding gene on chromosome 18 (50,968,019 to 51,058,144, forward strand). Ensembl gene ENSG00000267699.
Genetic constraint (gnomAD): Missense variants: 55 observed, 74.02 expected, observed/expected ratio (o/e) 0.74, 90% interval 0.6 to 0.93. Synonymous variants: 24 observed, 27.79 expected, observed/expected ratio (o/e) 0.86, 90% interval 0.62 to 1.21.